CYP2D6 (cytochrome P450 family 2 subfamily D member 6 (gene/pseudogene))
Diseases named in the same sentence as CYP2D6 in open-access papers (continued):
Sharing a sentence is not in itself a finding about the gene and the disease.
breast carcinoma (continued). "With the growth in understanding of the importance of cytochrome P450 2D6 (CYP2D6) polymorphism and its relationship with the therapeutic outcome of tamoxifen in patients with breast cancer, we can now partly attribute the unpredictable results from early melanoma studies to CYP2D6 polymorphism." (PMID 29308069, 2018). "For example, DPWG, but not CPIC, published guidelines for irinotecan dosing according to UGT1A1 genotype, whereas among the four regulatory agencies listed in the table, only Health Canada/Santé Canada (HCSC) requires CYP2D6 genotyping prior to the prescription of tamoxifen for breast cancer." (PMID 30328952, 2018). "In breast cancer therapy, tamoxifen has become an important drug in the treatment and prevention of recurrence in patients with estrogen receptor positive breast cancers; however, the generation of the potent metabolite, endoxifen, is dependent on CYP2D6 metabolism." (PMID 29868213, 2017). "In order to validate that T47D human breast cancer is suitable for this designed research, we firstly examined several human breast cancer cell lines whether they express CYP2D6 enzyme." (PMID 24886861, 2014). "It has been proposed that selective serotonin reuptake inhibitors (SSRIs) with potent CYP2D6 inhibitory activity may lead to decreased tamoxifen activity in patients with breast cancer." (PMID 25032007, 2013). "The data indicate that, although CYP2D6 polymorphisms can indeed modify tamoxifen pharmacokinetics, CYP2D6 genotyping alone is not enough for predicting breast cancer outcomes." (PMID 23346096, 2012). "Although there are no other reports suggesting any beneficial effect of CYP2D6 polymorphisms in relation to breast cancer outcomes, there is much inconsistency in the supposed detrimental effects of the variant alleles with regards to the risk of recurrence." (PMID 23346096, 2012). "Data suggest that women with the CYP2D6 poor metaboliser phenotype have worse breast cancer outcomes, and may have different tamoxifen-related toxicity profiles compared with women with a normal CYP2D6 activity." (PMID 19953095, 2010). "Previous studies have suggested that postmenopausal women with breast cancer who present with wild-type CYP2D6 may actually have similar or superior recurrence-free survival outcomes when given tamoxifen in place of aromatase inhibitors (AIs)." (PMID 21187922, 2010). "Important CYP2D6-inhibiting drugs are, for instance, selective serotonin reuptake inhibitors (SSRIs), which may be used in breast cancer patients to treat depression or hot flashes; a common side effect of tamoxifen." (PMID 20700120, 2010). "In conclusion, this study suggests that CYP2D6, mEH and NAT2 gene polymorphisms may be attractive susceptibility markers for breast carcinoma." (PMID 18423013, 2008). "In the present study we investigated the prognostic and/or predictive value of functional polymorphisms in cytochrome P450 3A5 CYP3A5 (*3), CYP2D6 (*4), sulphotransferase 1A1 (SULT1A1; *2) and UDP-glucuronosyltransferase 2B15 (UGT2B15; *2) in tamoxifen-treated patients with breast cancer." (PMID 17244352, 2007). "Moreover, previous evidence has shown that poor and ultrarapid CYP2D6 metabolizers of tamoxifen could predict worse clinical outcomes among patients with breast cancer treated with tamoxifen." (PMID 35252004, 2022). "In addition, a non-functional CYP2D6 variant was previously associated with higher recurrence rates in a breast cancer cohort." (PMID 34568059, 2021). "However, endoxifen formation largely depends on CYP2D6 functionality, and the WHEL study, despite its large sample size of 1370 participants, could only represent a small part of the global breast cancer population and its associated diversity." (PMID 34069810, 2021). "Finally, genotyping from formalin-fixed, paraffin-embedded specimens may not be as accurate as that from the DNA of blood lymphocytes, because somatic deletion at the CYP2D6 chromosomal locus is relatively common in breast cancer." (PMID 30734152, 2019).
breast carcinoma (continued). "Although there was a suggestion of a differential association of CYP2D6 genotype according to patient ethnicity, concomitant therapy, breast cancer stage/grade and menopause status, none of the subgroup analyses surpassed our a priori Bonferroni-adjusted P-value threshold of <0.002." (PMID 24098545, 2013). "Two other large studies involving breast cancer survivors who used tamoxifen also suggested the lack of association between CYP2D6 genotypes, or estimated CYP2D6 metabolizing phenotypes, and breast cancer outcomes." (PMID 23346096, 2012). "However, as part of our presentation to patients prior to testing, we showed the results of both prior positive and negative studies testing for associations between CYP2D6 and breast cancer." (PMID 21970596, 2011). "Patients who carry reduced-function or nonfunctional CYP2D6 alleles have been found to derive inferior therapeutic benefit from tamoxifen and thus are at increased risk of breast cancer recurrence or have significantly shorter disease-free survival than non-carriers." (PMID 21037853, 2010). "Therefore, the current study supports the TDM for breast cancer patients under tamoxifen treatment, since the effectiveness of the therapy is related to the levels of endoxifen, which is dependent on several unknown factors that go beyond CYP2D6 phenotype." (PMID 40910489, 2025). "The CYP2D6 genotype was determined in two groups of predominantly non-Hispanic white patients; 1514 contralateral breast cancer (CBC) cases and 2203 unilateral breast cancer controls." (PMID 33673305, 2021). "Tamoxifen metabolism pathway was found to be enriched in breast cancer patients involving UGT2B15, SULT1A1 and CYP2D6 genes." (PMID 33503040, 2021). "This study confirmed the safety and feasibility of using the Inje cocktail to assess the in vivo activity of CYP2C9, CYP2C19, CYP2D6, and CYP3A4 in women receiving chemotherapy for breast cancer (BC)." (PMID 33707475, 2021). "In oncology, CNVs in CYP2D6 are among the most frequently studied structural variations in connection with efficacy and ADR of tamoxifen treatment in breast cancer patients." (PMID 32872162, 2020). "We re-evaluated a comprehensive data set of CYP2D6 genotypes and TAM metabolite concentrations of breast cancer patients treated with adjuvant TAM to assess the prediction of impaired TAM metabolism by CYP2D6." (PMID 28955222, 2017). "Finally, direct administration of endoxifen to bypass CYP2D6-dependent bio-activation and to reduce inter-individual variability of endoxifen Css levels may be an attractive alternative in treatment of postmenopausal breast cancer." (PMID 24936398, 2014). "In this descriptive study, correlations were examined between concentrations of tamoxifen metabolites and genotypes for CYP2D6, CYP3A4, CYP3A5, SULT1A1, SULT1A2 and SULT1E1 in 135 patients with estrogen receptor-positive breast cancer." (PMID 23922954, 2013). "We have used two approaches to investigate the relation between germline variation in the CYP2D6 gene and BCSS and OS in breast cancer patients treated with tamoxifen." (PMID 20731819, 2010). "CYP2E1, CYP2C19, CYP2D6, mEH and NAT2 genotype frequencies in control subjects and in patients with breast carcinoma." (PMID 18423013, 2008). "We therefore investigated the genotypes of CYP2D6 and SULT1A1 in 226 breast cancer patients participating in a trial of adjuvant tamoxifen treatment in order to validate the benefit from the therapy." (PMID 15987423, 2005). "Conversely, individuals with low CYP2D6 activity and high CYP2C19 metabolism may experience shorter recurrence-free survival and breast cancer-specific survival, particularly among premenopausal women." (PMID 41295207, 2025). "Apoptosis induction of 40.12% was observed for compound 23j and it displayed good ADME characteristics including low BBB permeation, lack of CYP2D6 inhibition, and low plasma protein binding, favoring its application for the treatment of breast cancer." (PMID 40493694, 2025).
breast carcinoma (continued). "In the postmenopausal subgroup, CYP2D6 activity had no statistically significant influence on breast cancer recurrence (aHR1.44, CI 0.99; 2.07)." (PMID 40600576, 2025). "CYP2D6 has numerous endogenous substrates including tamoxifen, a selective estrogen receptor modulator (SERM) commonly used to treat estrogen receptor-positive (ER+) breast cancer." (PMID 40149251, 2025). "The results of this study suggest that CYP2D6 and CYP2C19 genotypes need to be tested in patients with breast cancer to allow physicians to tailor the treatment according to these genotypes, thereby reducing mortality rates and personalising the treatment of patients with breast cancer." (PMID 38681733, 2024). "The aim of this study was to investigate the frequency distribution of the cytochrome P450 (CYP450) enzymes, CYP2D6 and CYP2C19, and the form of tamoxifen metabolisation in premenopausal patients with breast cancer in the Han and Uygur ethnic groups of Xinjiang to guide rational clinical drug use." (PMID 38681733, 2024). "This also applied to the low-dose prevention study where CYP2D6 genotype was not related to the development of breast cancer precursor lesions in the breast." (PMID 36765172, 2023). "As a therapeutic drug for breast cancer, Tamoxifen (TAM) has better pharmacological activity only after the formation of 4-hydroxy-N-demethylamoxifen (Endoxifen), which is a metabolite catalyzed by CYP2D6." (PMID 36874034, 2023). "In other three included studies, negative association was found between CYP2D6*4 allele and survival rates (OS, PFS, DFS) of breast cancer patients (Refs 47, 59, 62)." (PMID 34991754, 2022). "On the contrary, the National Comprehensive Cancer Network (NCCN) Breast Cancer Panel along with the American Society of Clinical Oncology (ASCO) and the European Society for Medical Oncology (ESMO) recommend against using CYP2D6 genotype to guide the selection of adjuvant endocrine therapy." (PMID 36243690, 2022). "In a small prospective study of 12 women with breast cancer, the measured plasma concentrations of endoxifen were decreased by around twofold 4 weeks after the beginning of paroxetine (SSRI) intake, which means that CYP2D6 mediates endoxifen metabolism." (PMID 32821392, 2020). "The effectiveness of endoxifen, an active metabolite of tamoxifen, is independent of CYP2D6, and its unique therapeutic benefit was recently confirmed in patients with breast cancer." (PMID 29308069, 2018). "We found that expressions of certain CYP genes is correlated with node status (N stage) of breast cancer including CYP2A6 (p-value = 0.025), CYP2C8 (p-value = 0.035), CYP2D6 (p-value = 0.027), CYP2J2 (p-value = 0.036), CYP3A7 (p-value = 0.026), and CYP4B1 (p-value = 0.046)." (PMID 28684774, 2017). "T47D human breast cancer cells showed significant amount of CYP2D6 protein, while MCF-7 cells did not express detectable protein amount." (PMID 24886861, 2014). "The current evidence does not support the use of CYP2D6 genotyping to guide tamoxifen prescribing for the treatment of breast cancer." (PMID 24098545, 2013). "In addition to CYP2D6 metabolizing phenotype, the authors identified other variables, such as excess weight and low tamoxifen levels (suggesting failures in adherence), which were associated with low endoxifen levels, but not independently associated with breast cancer outcomes." (PMID 23346096, 2012). "Recent retrospective analyses from two large randomized trials comparing tamoxifen with aromatase inhibition as treatment for early stage breast cancer in post-menopausal women demonstrated no impact of CYP2D6 genotype on outcome." (PMID 21970596, 2011). "For example, depression is a common comorbidity in breast cancer patients and many selective serotonin reuptake inhibitors (SSRI), which are widely used medications indicated primarily to treat depression, are metabolized by CYP2D6." (PMID 18665165, 2008).
breast carcinoma (continued). "In a previous study we investigated functional polymorphisms in CYP2D6 and SULT1A1 in 226 postmenopausal patients with breast cancer randomised to treatment with or without tamoxifen." (PMID 17244352, 2007). "Improved systemic breast cancer treatment, not metabolized by CYP2D6, might compensate for reduced tamoxifen activation in patients with poorer CYP2D6 activity." (PMID 40600576, 2025). "The plasma concentration of endoxifen, the active metabolite of tamoxifen, might be affected by different CYP2D6 genotypes in patients with breast cancer, but solid evidence is still lacking in Asian patients." (PMID 40050768, 2025). "However, quantitative assessment of the influence of this in studies of CYP2D6 rs3892097 showed minor impact of genotype misclassification when investigating breast cancer survival." (PMID 35501422, 2022). "Lower expression of CYP2A6 and CYP2D6, involved in the metabolism of tamoxifen, tegafur and CPA may result in inefficient metabolism/activation of these agents which may affect survival of breast cancer patients as demonstrated in the current study." (PMID 33809117, 2021). "In the group that did not take tamoxifen, CYP2D6 genotype could not influence survival, which led to the conclusion that CYP2D6 activity cannot be used as prognostic marker for breast cancer, as it only can estimate the outcome with tamoxifen treatment." (PMID 32821392, 2020). "We used vilazodone for these experiments because unlike some other SSRI vilazodone does not inhibit CYP2D6, which is required for the conversion of the breast cancer pro-drug tamoxifen into its active metabolite endoxifen, nor does it affect CYP3A4 activity, which metabolizes many chemotherapeutics." (PMID 28404880, 2017). "Though speculative, it is conceivable that the expression status of ERβ1, which was not assessed in all of the CYP2D6 studies, could partially explain the conflicting predictive role of CYP2D6 pharmacogenomics and breast cancer outcomes." (PMID 24324894, 2013). "However, the impact of such pharmacokinetic changes on the individual degree of response to tamoxifen is less clear, and CYP2D6 genotyping alone has been not enough for predicting breast cancer outcomes in clinical settings." (PMID 23346096, 2012). "Perhaps most importantly, our studies reveal that even low concentrations of endoxifen, mimicking that of poor and intermediate CYP2D6 metabolizers, results in repression of estrogen induced breast cancer proliferation in cells expressing ERβ, but not in those that express only ERα." (PMID 21392396, 2011). "Thus, this study aimed to investigate, in a large real-world population with long follow-up, the impact of the tamoxifen dose coverage, CYP2D6*4 haplotype, and concomitant use of SSRIs, in addition to other non-genetic factors, on tamoxifen-treated breast cancer survival." (PMID 40452016, 2025). "In a study of 80 newly diagnosed breast cancer patients commencing TAM adjuvant treatment, the plasma concentrations of endoxifen after four months were lower in patients homozygous or heterozygous for non-functional CYP2D6 alleles compared to those with two functional alleles." (PMID 27713292, 2010). "SSRI competition with tamoxifen and N-desmethyltamoxifen for CYP2D6, or direct inhibition of CYP2D6 by SSRI, could reduce the production of the tamoxifen metabolites with high receptor-binding affinity, and thereby reduce tamoxifen’s prevention of breast cancer recurrence." (PMID 18665165, 2008). "The present study found no significant racial differences in terms of CYP2D6*5, CYP2C19*1, CYP2C19*3 and tamoxifen metabolism types among Han and Uygur premenopausal patients with breast cancer in Xinjiang." (PMID 38681733, 2024). "The aim of the present study was to investigate the genotypes of CYP2D6 and SULT1A1 in breast cancer patients with and without tamoxifen treatment in order to validate the relation between the genotype and the benefit from tamoxifen therapy." (PMID 15987423, 2005).
depression (57 papers, 2008 to 2026). "A study on patients with recurrent depression found that an SNP in CYP2D6 was associated with the efficacy of the antidepressant duloxetine." (PMID 37581520, 2024). "The CYP2D6 genotype has also been shown to have a possible impact on the length of hospitalization and risk of hospitalization in patients with major depressive disorder, thereby increasing the disease and financial burden on patients." (PMID 37581520, 2024). "CYP2D6 gene had the largest number of drugs affected by its polymorphism forms with disease conditions such as depression, psychosis, pain, and epilepsy." (PMID 38535119, 2024). "Behavioral tests revealed that CYP2D6-transgenic mice were also less susceptible to anxiety and depression, which is in line with an important role of serotonin in those mental disorders." (PMID 37233670, 2023). "We have studied the association between CYP2C19 and CYP2D6 gene variants and the treatment outcomes in children and adolescents, young adults, and adults with depression who were using (es)citalopram, sertraline, or fluoxetine." (PMID 35890168, 2022). "This is especially noticeable for those patients with only one functional CYP2D6 allele, as studied in 50 Caucasians with depressive disorder." (PMID 35745763, 2022). "Secondly, the work was conducted in a set of samples from European individuals being treated for depression, with samples being selected as being representative for genotypes available in the whole set and with enrichment for CYP2D6 structural variants." (PMID 34811360, 2021). "Question: Do women with certain CYP2D6 genotypes have higher risk of antidepressant discontinuation, dosage modifications, depression during pregnancy?" (PMID 28769788, 2017). "Current guidelines for the use of genetic tests in major depression issued by the Clinical Pharmacogenomics Implementation Consortium (CPIC) are based on CYP2D6 and CYP2C19 polymorphisms which constitute the strongest evidence for pharmacogenomic guided treatment." (PMID 37490261, 2023). "In this case, the CSN identifies and presents complaints (depression) that might have pharmacologic root cause (serotonergic burden) likely due to a CYP2D6 variant rendering the patient a poor metabolizer of ondansetron and cyclobenzaprine." (PMID 34063850, 2021). "Among CYP2D6 opioid users, the presence of CYP2D6 interacting drugs was associated with substantial differences in the prevalence of individuals having anxiety (14.21 vs. 6.49%), depressive disorders (56.85 vs. 10.28%), anti-epileptic drugs (27.38 vs. 9.40%), and GERD (27.90 vs. 9.85%) (p < 0.001)." (PMID 34834526, 2021). "Increased CYP2D6 metaboliser status (faster drug clearance) was shown to lower the odds of symptom improvement in young people treated with Fluoxetine for managing major depressive disorder or OCD." (PMID 41009999, 2025). "For example, if a patient who has CYP2D6 normal metabolizer status and their pain has been well-controlled on tramadol now gets prescribed paroxetine (a strong CYP2D6 inhibitor) for depression." (PMID 40710411, 2025). "64% of the patients with an IM or PM phenoconverted phenotype of CYP2D6 experienced the side effect depression compared to 30.4% NMs and UMs (p = 0.020)." (PMID 37693320, 2023). "In fact, patients with duplicated CYP2D6 presented with low-serum concentration of paroxetine for depression treatment or lower plasma concentration of donepezil while no clinical improvement observed in Alzheimer's treatment." (PMID 37719322, 2023). "An association between CYP2D6 and CYP2C19 phenotypes and adverse effects secondary to TCA intake has been repeatedly described for patients treated for depression." (PMID 35745763, 2022). "Venlafaxine is extensively metabolized to desvenlafaxine via CYP2D6, which is also used as a stand-alone treatment for major depressive disorders, while paliperidone is the major active metabolite of risperidone." (PMID 34281235, 2021).